SST (somatostatin)
Diseases named in the same sentence as SST in open-access papers (continued):
Sharing a sentence is not in itself a finding about the gene and the disease.
tumor (continued). "In vitro studies and in animal models of CRC indicate the involvement of SST in reducing the number of tumor blood vessels in connection with antiproliferative and pro-apoptotic effects and inhibition of VEGF expression." (PMID 38540191, 2024). "When PRRNT in the form of β emitters such as lutetium-177-DOTATATE therapy is administered, the radiolabeled somatostatin analogs bind to the somatostatin receptors on tumor cells." (PMID 38933067, 2024). "The tumor-accumulation capability of radiolabeled functionalized NDs was investigated and compared with [68Ga]Ga-DOTA-TOC as the “gold standard” in mice bearing a somatostatin overexpressing subcutaneous tumor." (PMID 38675474, 2024). "When comparing the analyzed SST and SSTRs based on tumor size (T parameter) at diagnosis, significant differences were found only for SST2 immunoexpression (p = 0.017) (Kruskal–Wallis test)." (PMID 39518025, 2024). "Some studies have also reported that HMOX1, SST, PLA2G2A, KRT4 and COL3A1 are associated with tumor progression and prognosis." (PMID 38461430, 2024). "SST analogs in vivo can regulate tumor growth through direct and indirect actions, inhibiting the secretion of GH, growth factors, and angiogenesis." (PMID 39518025, 2024). "The role of SST in tumor genome/tumor microenvironment (TME)/host’s gut microbiome interactions is only partially known." (PMID 38540191, 2024). "Adjunctive therapy with synthetic long‐acting somatostatin (SST) analogues has been described in humans with SST‐expressing tumours." (PMID 39011594, 2024). "When the promoter of SST is hypermethylated in midgut NENs, the somatostatin protein has reduced expression and consequently reduced the ability to inhibit tumor growth." (PMID 38123518, 2024). "Treatment with somatostatin analogues is well established because of their analgesic effect beyond simply tumor size reduction, suggesting that somatostatin analogues have a biochemical inhibitory effect on pronociceptive peptides." (PMID 39129819, 2024). "In comparison, the internalizing somatostatin agonist [161Tb]Tb-DOTATOC was only 5-fold more effective in inhibiting tumor cell viability than the 177Lu-counterpart." (PMID 38389843, 2024). "The expression of SSTR subtypes has been reported in human SCLC cells, suggesting a possible role of SST in modulating tumour growth." (PMID 38203605, 2023). "Inconsistent expression of SSTRs has been detected in different pituitary tumours, which resulted in a significant difference in response of SST/analogues efficiency to regulate tumour growth." (PMID 38203605, 2023). "The binding of the SST to five different receptors exerts an inhibitory role on tumour progression and cell proliferation." (PMID 38203605, 2023). "When H-69 SCLC cell line xenografts expressing mRNA for SSTR2 were introduced in nude mice and subsequently treated with an SST analogue AN-238, tumour growth was inhibited." (PMID 38203605, 2023). "In one study, tumor progression in mid- to late-stage, somatostatin inhibitor receptor-positive patients is effectively blocked by lanreotide, providing good symptom control Molecular target therapy is based on gene mutations widely found in PNETs." (PMID 37296397, 2023). "Prior to delineating the direct and indirect effect of SST and its analogues in the suppression of cell proliferation, induction of apoptosis and regulation of tumour-promoting signaling pathways, several radiolabels were used for diagnosis purposes." (PMID 38203605, 2023). "SST-14 analogues such as OCT have been successfully demonstrated as an antiproliferative agent in different tumour models, including the prostate and pancreas." (PMID 38203605, 2023). "The expressions of SSTRs, which act as therapeutic targets for SST analogs, which can slow tumor growth and suppress hormone overproduction, are one inherent characteristic of NETs." (PMID 37900156, 2023).
tumor (continued). "SST hypermethylation, with subsequent decrease in gene expression, has been observed in 81% of HNSCC samples and has been linked to tumor extent, disease stage, galanin type 2 receptor (GALR2) methylation, and tachykinin-1 (TAC1) methylation." (PMID 36769317, 2023). "Although, the 161Tb-labeled SST agonist DOTATOC was only fivefold more effective inhibiting tumor cell viability than its 177Lu-counterpart." (PMID 36952073, 2023). "In this review, with the recent development of new SST analogues and receptor-specific agonists with emerging functional consequences of signaling pathways are promising therapeutic avenues in tumours of different origins that are discussed." (PMID 38203605, 2023). "The inhibition of angiogenesis seems to be an effective indirect mechanism of SST-mediated negative regulation of tumour growth." (PMID 38203605, 2023). "Visualization of specific tumor cells that express SSTR is achieved by attaching a radioactive isotope (68Gallium) with quick radioactive decay to a ligand (the stable somatostatin analogue: DOTATOC or DOTATATE) that binds to SSTR." (PMID 37568733, 2023). "The use of peptide receptor radiolabeled compound is well established, and SST is one that has been used frequently for multiple types of tumours." (PMID 38203605, 2023). "Past studies, in addition to the inhibition of gonadotropins secretion in in vivo and in vitro, have also shown tumor shrinkage with the use of DA agonist and SST analogues either used alone or in combination." (PMID 38203605, 2023). "Somatostatin (SST), a growth hormone (GH)-inhibitory peptide, inhibits tumour cell proliferation and induces the prompt shrinkage of most tumours via binding to five different receptor subtypes that play an important role in a wide range of tumour treatment." (PMID 38203605, 2023). "Out of which, the SSTR2 and SSTR5 have gained significant attention due to their role in mediating the inhibition of growth hormone and antiproliferative effects of somatostatin on tumor growth." (PMID 37770425, 2023). "SST and its analogs are involved in improving patients’ life span and comfort, in addition to the direct and indirect role that SST plays in tumour growth suppression." (PMID 38203605, 2023). "As expected, all genes were lowly expressed in tumor tissues of multiple validation data sets, except for DEFB1 and SST, which were highly expressed in tumor tissues." (PMID 37318692, 2023). "Binding specific G-protein-bounded somatostatin receptors SST inhibits secretion of many hormones as well as tumor cell growth." (PMID 37111609, 2023). "Post-release from secretory or immune cells, the first most appreciated role that SST exhibits is the antiproliferative effect in target tissue that served as a potential therapeutic intervention in various tumours of different origins." (PMID 38203605, 2023). "Of the eight IRGs, only DEFB1 and SST were highly expressed in tumor tissues, while the other six genes were lowly expressed." (PMID 37318692, 2023). "SST binds to certain cell surface receptors to suppress exocrine and endocrine secretions as well as tumor cell growth." (PMID 37900156, 2023). "Long-acting somatostatin analogues were effective in inhibiting tumor growth in randomized phase III trials (CLAIRNET and PROMID) and are used to treat metastatic, well-differentiated aNETs." (PMID 37956190, 2023). "SST, a cyclic polypeptide, is not only involved in the maintenance of internal environment homeostasis but also acts as a tumor suppressor in multiple cancers." (PMID 36863706, 2023). "Taken together, these results indicated that the BRAFV600E/AktDD tumor parenchyma comprises lower fractions of parvalbumin- and somatostatin-positive interneurons." (PMID 36538906, 2022). "The purpose of this review is to summarize information about the role of somatostatin signalling in NETs, as well as the development, prognosis, and treatment for these tumours." (PMID 35163374, 2022).
tumor (continued). "The anti-angiogenic effects of SST and its analogues are mainly observed in tumour angiogenesis, where SST2 and SST3 receptors are predominant." (PMID 35328517, 2022). "Our data demonstrated a reduction of the fraction of parvalbumin- and somatostatin-expressing interneurons in the BRAFV600E/AktDD tumor parenchyma also in the GG mouse model." (PMID 36538906, 2022). "While only a few patients with NETs are amenable to curative tumor resection, for many patients, only palliative treatments remain, such as with somatostatin (SST) or SST analogs (SSAs), such as octreotide (OCT) or lanreotide (LAN)." (PMID 36555512, 2022). "In recent studies, other epigenetic regulators affecting SST signalling or SSA–mTOR inhibitor combination therapy in NETs have been considered as novel strategies for tumour control." (PMID 35163374, 2022). "Due to the safety and efficacy of the oncolytic virus VG9/TK−, we applied this promising transgenic vector to express somatostatin fusion protein, and the therapeutic effects of both somatostatin and oncolytic virus were combined to destroy tumor tissues." (PMID 36207478, 2022). "This technology avoids the terminal degradation of somatostatin protein and the complicated purification process, while the tumor tropism of vaccinia virus can transport the fusion protein to the tumor region and exert a better anti-tumor effect." (PMID 36207478, 2022). "One of the intrinsic properties of NETs is the expression of SSTRs that serve as drug targets for SST analogues (SSAs), which can delay tumour progression and downregulate hormone overproduction." (PMID 35163374, 2022). "Intriguingly, the somatostatin-positive cells were significantly more abundant in the perilesional tissue compared to the tumor parenchyma (online suppl." (PMID 36538906, 2022). "Histology of the tumor specimen confirmed a somatotroph tumor and somatostatin (SST) receptor subtyping using an immunoreactivity score (IRS) of 17 to 18, membranous expression of IRS 1 for SST2 receptor and IRS of 12 for SST5 receptor." (PMID 35090028, 2022). "Even though AR42J tumor cells show neuroendocrine properties and have, thus, been extensively employed for the evaluation of SST analogues, it can be considered a limitation of this study to have only used rat tumor cells." (PMID 34625828, 2022). "SSTRs are present both in normal and in tumor tissues which enables their response to applied SST analogs (SSA)." (PMID 35887747, 2022). "Among the analogs of peptide hormones, somatostatin (SST) analogs were found to decrease tumor cell growth and angiogenesis and increase cancer cell apoptosis." (PMID 35326723, 2022). "Conversely, more and more evidence suggests that somatostatin, a gastrin antagonist, has potent antitumor effects, with the somatostatin encoding gene SST considered to be a tumor suppressor susceptible to epigenetic silencing in several cancers." (PMID 35899973, 2022). "Preclinical therapy studies with AR42J tumor-bearing mice confirmed the superior efficacy of 161Tb-labeled SST analogues over those labeled with lutetium-177." (PMID 34625828, 2022). "It was observed that, in all cases, the 161Tb-labeled SST analogue was more potent in reducing AR42J tumor cell viability than the 177Lu-labeled analogue." (PMID 34625828, 2022). "SST is also a powerful inhibitor for tumor cell proliferation, severe inflammation, and perioperation, and is listed as a first-line anti-cancer drug in clinical practice." (PMID 33796080, 2021). "Performance of 68Ga-labeled somatostatin (SST) PET/CT is based on the membranous overexpression of somatostatin receptors (SSTRs) on the tumor cell." (PMID 35008325, 2021). "SSTR2 is widely considered the most important mediator of SST antiproliferative functions, which include induction of cell cycle arrest and apoptosis as well as inhibition of tumor angiogenesis and growth factor (e.g., VEGF and IGF-1) expression." (PMID 34680266, 2021).
tumor (continued). "In fact, anticancer drugs such as cisplatin, arbutin, somatostatin, and prednisolone exert anti-tumor activity by regulating VDAC132–35." (PMID 33602982, 2021). "Both normal and tumor-bearing populations of males contained one animal with somatostatin levels elevated greater than two SD above the mean of the control population, again falling within the natural expected Gaussian curve." (PMID 34862365, 2021). "As mentioned, the local effects (paracrine, autocrine) of endogenous SST mostly involve inhibition of cell proliferation versus promotion of apoptosis, and inhibition of production and secretion of many other tumor growth factors." (PMID 34829972, 2021). "Little is known about precursor lesions of ampullary-type somatostatin-producing NETs; however, scattered somatostatin cells forming linear or micronodular growths have been described in the normal ampullary epithelium adjacent to neoplasms." (PMID 33922305, 2021). "In these studies, the frequency of detection of SST in tumor and control tissues was similar or reduced in CRC vs. control." (PMID 34829972, 2021). "In conclusion, understanding of the epigenetic mechanisms involved in the regulation of the expression of the SST-system is important for both NETs and other tumor types." (PMID 33085037, 2021). "Administration of somatostatin can decrease intestinal secretion by direct reduction of release of the secretagogue from the tumor." (PMID 33398457, 2021). "It was demonstrated a progressive increase in SST gene promoter methylation starting from juvenile colonic epithelium and ending on tumor-transformed epithelium in CRC." (PMID 34829972, 2021). "All PanNETs examined expressed insulin in the tumor mass and a few also exhibited expression of glucagon and somatostatin." (PMID 34862365, 2021). "This SSTR upregulation in NET cells facilitates SSTR targeting by SST analogues (SSAs) to limit tumor cell hormone secretion and proliferation while additionally enabling use of radiolabeled SSAs for NET imaging and therapy." (PMID 34680266, 2021). "The SST (somatostatin) protein functions as a tumor suppressor in various tumor types through binding to somatostatin receptors." (PMID 33782686, 2021). "The binding of somatostatin to SSTR-expressing tumor cells leads to tumor regression by reducing cell proliferation and inducing apoptosis." (PMID 32545257, 2020). "In all the eventually 10 tumor types looked at, there were strong SST hypermethylation and downregulation of SST expression." (PMID 32243066, 2020). "Pancreatic cancer CNR was found to be significantly increased by targeting somatostatin 20,21 or tumor cell antigens 22 or utilizing cell-penetrating peptides 23 for tumor-specific enhancement." (PMID 32206099, 2020). "In this context, it has been reported that somatostatin mRNA levels were significantly lower in the tissue of gastric cancer when compared to non-tumor tissue." (PMID 32545257, 2020). "SST promoter methylation represents a sensitive and promising molecular, pan‐cancer biomarker detectable in tumor tissue, and liquid biopsy samples." (PMID 32243066, 2020). "Quantification by direct bisulfite sequencing of the amplified SST 464‐bp region showed that an average 37.2% of CpGs in tumor samples were methylated while only 2.2% methylation was observed in normal pancreas tissues." (PMID 32243066, 2020). "In several pathological conditions, including tumours of different origin, HIV, etc., the loss of appetite is the major problem while SST and its analogues provide a potential therapeutic option." (PMID 32272767, 2020). "Somatostatin (SST) plays an important role in regulating the proliferation of normal cells and tumor cells." (PMID 32974188, 2020). "SST inhibits tumor cell growth arrest and hormone secretion through binding of five different SST receptors." (PMID 31191457, 2019).
tumor (continued). "Various somatostatin analogs have been conjugated to radioactive chemotherapeutic agents to induce tumor death by a process termed peptide receptor radionuclide therapy (PRRT)." (PMID 31091786, 2019). "It is thus probable that patients treated with long acting SST analogues are undertreated during the first few months, during which tumor progression is evident." (PMID 31569719, 2019). "SSR antagonists promise a higher binding affinity for somatostatin positive tumor cells, thus leading to an increasing radiation dose within the tumor." (PMID 31234481, 2019). "The SST analogs are the primary medical therapy to treat acromegaly for maintenance of GH homeostasis and shrinkage of tumor size." (PMID 31231308, 2019). "Now the patient is almost a year after being diagnosed with a tumor, after completion of 6 cycles of adjuvant chemotherapy (carboplatin + etoposide) in combination with biological therapy, the long-acting somatostatin analogues." (PMID 30902091, 2019). "The great majority of GEP-NENs, as well as approximately 50% of small intestine NETs and insulinomas, express multiple SST subtypes involved in hormone secretion and tumor cell growth." (PMID 31412614, 2019). "Biological treatment with somatostatin analogues is a new modality for modifying the disease, in particular in cases of confirmed somatostatin receptor expression on the surface of tumor cells." (PMID 30902091, 2019). "SST plays an essential role in human tumor suppression by both direct and indirect mechanisms, for example, acting as a tumor gene suppressor with antitumor effects." (PMID 29854027, 2018). "For example, SST acts as an antitumoral agent as it inhibits growth factors, reduces vasculature, and regulates the immune system, behaving as a tumor suppressor both in vitro and in vivo." (PMID 29854027, 2018). "The fourth approved indication for SST analogs in patients with NETs is their use to target cytotoxic radiolabeled SST analogs to the tumor in patients with advanced NETs, as an anti-tumor therapy (called PRRT for peptide receptor radionuclide therapy)." (PMID 30008698, 2018). "In this study, SST was considered for further investigation because of the potential tumor-suppressor activity of this antiproliferative hormone." (PMID 29700299, 2018). "The epithelial cell cluster unique to patient HG3 from this tumor had eleven differentially expressed genes with highest expression found in SST, TFF3 and PIGR." (PMID 30383866, 2018). "SST and the somatostatin receptors have been identified as tumor suppressor genes that possess potent antitumor and antisecretory activities in several human cancers." (PMID 29682090, 2018). "Almost all of the early studies performed with SRI and PRRT used SST analogs that were agonists because of the belief the peptide should be internalized to provide the best imaging and radionuclide delivery to the tumor." (PMID 30008698, 2018). "Cyclooxygenase-2 inhibitors and somatostatin analogues were reported to inhibit tumour angiogenesis." (PMID 28430638, 2017). "The resulting SST analogue was radiolabelled with 64Cu, and its in vitro and in vivo properties in A427-7 tumour-bearing Balb/c mice were compared against those of 64Cu-DOTA-Tyr3-octreotate." (PMID 28804185, 2017). "Hypermethylation was correlated to high recurrence of tumours in a 56-month median follow-up study of serum SST and MAL." (PMID 29038612, 2017). "Angiogenesis inhibition and tumor growth regulation events are both indirect effects of somatostatin." (PMID 27734947, 2016). "The HT29 cells, which were originally derived from a low grade, well-differentiated tumor, expressed SST and all five of its receptors, but the SW480 cells, which were originally derived from a high grade undifferentiated tumor, did not express SST or SSTR5." (PMID 27927191, 2016).